ACTRT1 (actin related protein T1)
Description:
Negatively regulates the Hedgehog (SHH) signaling. Binds to the promoter of the SHH signaling mediator, GLI1, and inhibits its expression.
Synonyms: ARP-T1; ARPT1; HSD27; AIP1; KIAA0705; ARIP1
Tractability: No criterion of Open Targets' tractability assessment is met for any kind of drug.
Gene: Protein-coding gene on chromosome X (128,050,962 to 128,052,403, reverse strand). Ensembl gene ENSG00000123165.
Subcellular location: Cytoplasm, cytoskeleton; Cytoplasm; Nucleus; Cytoplasmic vesicle, secretory vesicle, acrosome
Gene Ontology:
Molecular function: chromatin binding; structural constituent of cytoskeleton
Biological process: negative regulation of DNA-templated transcription; regulation of smoothened signaling pathway; regulation of DNA-templated transcription; cytoskeleton organization
Cellular component: acrosomal vesicle; cytoplasm; nucleus; actin cytoskeleton; perinuclear theca; cytoskeleton
Homologues: Orthologues: chimpanzee ACTRT1 (99% identical), macaque ACTRT1 (95% identical), pig ACTRT1 (81% identical), guinea pig ACTRT1 (76% identical), rat Actrt1 (71% identical), mouse Actrt1 (70% identical). Paralogues in human: ACTRT2 (76% identical), ACTB (48% identical), ACTG1 (48% identical), ACTA1 (47% identical), ACTA2 (47% identical), ACTG2 (47% identical), ACTC1 (47% identical), ACTBL2 (47% identical), ACTRT3 (43% identical), ACTR1B (40% identical), ACTR1A (39% identical), ACTR2 (37% identical), and 14 more.
Diseases named in the same sentence as ACTRT1 in open-access papers:
ACTRT1 is named in the same sentence as 18 diseases in open-access papers, as found by Europe PMC text mining. Sharing a sentence is not in itself a finding about the gene and the disease. The quoted sentences say what the papers report.
basal cell carcinoma (5 papers, 2019 to 2024). A carcinoma involving the basal cells. "Loss of ACTRT1 function was reported to lead to aberrant activation of Hedgehog signalling in basal cell carcinoma." (PMID 38279874, 2024). "A recent study found that, mutations in the eRNA element of ACTRT1 in basal cell carcinoma can weaken the enhancer’s activity as well as the expression of ACTRT1, resulting in the aberrant activation of Hedgehog signaling and, consequently, the promotion of carcinogenesis and tumour development." (PMID 34238250, 2021). "It has been shown in basal cell carcinoma that mutations in the eRNA elements of ACTRT1 could impair enhancer activity and ACTRT1 expression, leading to aberrant activation of Hedgehog signaling and the contribution to tumor development." (PMID 30862109, 2019). "Actin-Related Protein-Testis1 (ARP-T1)/ACTRT1 gene mutations cause the Bazex-Dupré-Christol Syndrome (BDCS) characterized by follicular atrophoderma, hypotrichosis, and basal cell cancer." (PMID 33972689, 2021).
acephalic spermatozoa syndrome (2 papers, 2021 to 2025). "They identified 2 unrelated individuals with hemizygous missense variants in ACTRT1 in a cohort of 34 infertile men with acephalic spermatozoa syndrome (ASS)." (PMID 41465095, 2025). "In summary, we identified pathogenic variants of ACTRT1 in two idiopathic patients with acephalic spermatozoa syndrome." (PMID 34422805, 2021). "Therefore, our results demonstrated that pathogenic variants in ACTRT1 are a novel pathogenic mechanism of acephalic spermatozoa syndrome." (PMID 34422805, 2021). "Thus, we speculated that defects in ACTRT1 are a novel pathogenic mechanism of acephalic spermatozoa syndrome." (PMID 34422805, 2021). "Therefore, our results indicated that ACTRT1 is essential for the normal formation of the sperm head-tail junction, and defects in this gene may be involved in the etiology of acephalic spermatozoa syndrome." (PMID 34422805, 2021).
Bazex-Dupre-Christol syndrome (2 papers, 2021 to 2025). Bazex-Dupre-Christol syndrome is a rare genodermatosis (hereditary skin disease) with a predisposition to early-onset basal cell carcinomas. "Another example is Bazex-Dupré-Christol syndrome, caused by mutations in ACTRT1, which similarly affects the HH pathway." (PMID 40026985, 2025). "The insertion mutation, c.547_548insA, in ACTRT1 has been identified in two of six families with Bazex-Dupré-Christol syndrome, suggesting that mutations in ACTRT1 are likely to cause human disease." (PMID 34422805, 2021). "Insertion mutations (c.547_548insA, p.Met183Asnfs∗17) have been identified in transcribed sequences encoding enhancer RNAs of ACTRT1 in two families with Bazex-Dupré-Christol syndrome." (PMID 34422805, 2021).
Azoospermia (1 paper, 2025). Absence of any measurable level of sperm,whereby spermatozoa cannot be observed even after centrifugation of the semen pellet. "As demonstrated by the literature, male patients with hemizygous variants in the ACTRT1 gene exhibit a remarkably heterogeneous clinical spectrum, ranging from asthenoteratozoospermia and acephalic spermatozoa syndrome to severe oligozoospermia and non-obstructive azoospermia with meiotic arrest." (PMID 41465095, 2025).
ciliopathy (1 paper, 2021). A genetic disorder of the cellular cilia or the cilia anchoring structures, the basal bodies, or of ciliary function. "Thus, BDCS is a novel and first ciliopathy implicated in skin cancer caused by mutations of ACTRT1 or its enhancer RNA elements." (PMID 33972689, 2021).
gastric cancer (1 paper, 2024). A primary or metastatic malignant neoplasm involving the stomach. "In addition, gastric cancer patients were likely to have mutations in CDH1, ACTRT1, GANAB, and CDH10 genes in the High-CCDC80 group." (PMID 38872096, 2024).
infertile (1 paper, 2025). "They reported two infertile Chinese men with a ~110 kb X-chromosome microdeletion encompassing the entire ACTRT1 gene." (PMID 41465095, 2025). "The phenotypic spectrum of ACTRT1-related infertility may extend beyond acrosomal defects to include nuclear abnormalities and other sperm morphology defects, which could contribute to the variability observed in clinical outcomes and assisted reproductive technology (ART)." (PMID 41465095, 2025).
male infertility (1 paper, 2025). The inability of the male to effect fertilization of an ovum after a specified period of unprotected intercourse. "These efforts are essential for delineating precise genotype–phenotype correlations and understanding the full pathogenic potential of ACTRT1 gene variants in human male infertility." (PMID 41465095, 2025). "This makes it difficult to determine whether acrosome detachment is a universal feature of male infertility in patients with ACTRT1 deficiency." (PMID 41465095, 2025). "A comprehensive review of the Online Mendelian Inheritance in Man (OMIM) database revealed no established associations between the ACTRT1 gene and male infertility." (PMID 41465095, 2025).
oligoasthenoteratozoospermia (1 paper, 2025). A form of male infertility that is characterized by a combination of low number or oligozoospermia, poor motility or asthenozoospermia, and abnormal shape or teratozoospermia of sperms. "This study provides a comprehensive clinical and genetic characterization of a novel ACTRT1 gene variant in a patient with severe oligoasthenoteratozoospermia, acrosome abnormalities, and fertilization failure." (PMID 41465095, 2025).
cancer (2 papers, 2021 to 2022). A tumor composed of atypical neoplastic, often pleomorphic cells that invade other tissues. "Research has shown that the eRNA of ACTRT1 can lower the expression of target genes and promote the development of cancer." (PMID 35571043, 2022).
ACTRT1 also shares sentences with these, for which no sentence is quoted: tumor (3 papers); hypotrichosis (2); genetic disorder (1); hypohidrosis (1); multiple basal cell carcinomas (1); Renal cyst (1); skin cancer (1); teratozoospermia (1).